POLG (DNA polymerase gamma, catalytic subunit)
Diseases named in the same sentence as POLG in open-access papers (continued):
Sharing a sentence is not in itself a finding about the gene and the disease.
mitochondrial disease (continued). "In addition, although 140 POLG mutations have been described in patients with symptoms that suggest mitochondrial disease, most of mutations are reported in heterozygous in whom each POLG allele can be one or more different mutations and only few of these has been replicated in not related families." (PMID 23324391, 2013). "This study showed that SLE in genetically diagnosed mitochondrial diseases are most commonly observed in MELAS and POLG mutations." (PMID 41438888, 2025). "POLG-related mitochondrial diseases are clinically heterogeneous and can manifest at any age, with an early onset associated with an extremely poor prognosis." (PMID 37259148, 2023). "There are numerous reasons why the POLG gene should be considered the most important target for genetic analysis in case of mitochondrial disease and its genetic counselling." (PMID 33396418, 2020). "Individuals harboring POLG-, TYMP-, or MPV17- deletions or m.8993T>G and m.8993T>C mtDNA mutations, as well as those affected by SURF1-related mitochondrial diseases are at greater risk of developing peripheral neuropathy." (PMID 33383961, 2020). "Focal status epilepticus in POLG‐related mitochondrial disease is highly refractory to pharmacological agents, including general anesthesia." (PMID 29588995, 2018). "These mutants also revealed tissue-specific mtDNA depletion, reflecting the tissue differences found in human POLG mitochondrial disease." (PMID 26519465, 2015). "Screening of POLG gene in mitochondrial diseases is helpful for confirming the diagnosis, especially in the case of AHS." (PMID 21235791, 2011). "In an analysis of 112 patients with mitochondrial diseases and no POLG mutations, eight variants were observed, seven of which were novel heterozygous PolG2 disease variants." (PMID 41226312, 2025). "With the exception of SSBP1, a key component of the mitochondrial replication fork, to date, all nuclear genes directly involved in mtDNA replication (POLG, POLG2, TWINKLE, RNASEH1, DNA2, MGME1) have been associated with mitochondrial disease, mtDNA depletion, and/or mtDNA deletion." (PMID 31550237, 2020). "This suggests that the pluripotent stage is not suitable for modeling mitochondrial disease caused by POLG mutation." (PMID 32840960, 2020). "Given that POLG mutations are the most prevalent single gene cause of mitochondrial disease and there is a lack of any evidence-based therapies, understanding translation dynamics of its mRNA is important." (PMID 32138667, 2020). "Three groups of patients with mitochondrial disease were assessed (single large-scale mtDNA deletion and multiple mtDNA deletions due to pathogenic OPA1 and POLG mutations) in single muscle fibers laser captured in transverse and longitudinal sections of muscle biopsies." (PMID 30076399, 2018). "Mutations in SURF1 and POLG have been identified in patients with mitochondrial disease and hypertrophic olivary degeneration, but are not a consistent finding." (PMID 25887401, 2015). "However, new models are needed to address the progression of POLG mitochondrial disease, especially during early development, as many POLG-related mitochondrial diseases occur in childhood." (PMID 26519465, 2015). "This places POLG as a major locus for mitochondrial diseases and disorders." (PMID 22470557, 2012). "Since a therapy has not been yet developed for mitochondrial diseases caused by POLG mutations, a major goal of the research involving yeast/animal models is to find new strategies to rescue the pathological phenotypes associated to these mutations." (PMID 22470557, 2012). "However, the role of astrocytes in mitochondrial diseases such as POLG has yet to be explored." (PMID 38904024, 2024). "Negative POLG deletion and duplication tests, as well as an absence of the condition in other family members, indicated that the variant was novel and caused an autosomal recessive mitochondrial disease with the SANDO phenotype." (PMID 29644085, 2018).
mitochondrial disease (continued). "The significance of POLG mutations in another case of serrated dysplasia, NOS (patient #11), which are associated with a wide variety of mitochondrial diseases, remains uncertain, as they have not been previously linked to any serrated lesions." (PMID 40565166, 2025). "Normal muscle biopsy findings would not exclude the diagnosis of POLG-related mitochondrial disease, and direct sequencing of the POLG gene should be the gold standard when the clinical feature suggests POLG disease." (PMID 33113942, 2020). "To conclude, although POLG-related disorders are well-recognized mitochondrial diseases, they are possibly underdiagnosed due to their diverse, overlapping, and late-onset manifestations, particularly if standard panels not including POLG are used." (PMID 41245005, 2025).
cancer (19 papers, 2013 to 2026). A tumor composed of atypical neoplastic, often pleomorphic cells that invade other tissues. "POLG encodes DNA polymerase γ, the key enzyme responsible for mtDNA replication and repair in mitochondria, and its dysregulation has been closely associated with the development and progression of different cancers." (PMID 41293266, 2025). "NAD(P)H FLIM images of control and cyanide-treated WT and POLG BMDMs were input into the glycolysis vs OXPHOS FLI-LeNet models previously trained with MCF7 cancer cell images." (PMID 38420625, 2024). "Together, our data indicated that curcumin inhibited cancer cell growthvia decreasing POLG, thereby reducing mtDNA content, which further suppressed cellular bioenergetics." (PMID 28359291, 2017). "Collectively, our in vivo data validate the anti-cancer effects and POLG/cellular bioenergetics-involved mechanism of curcumin." (PMID 28359291, 2017). "Pathogenic or likely pathogenic variants in cancer-associated genes were identified in 37 (6.8%), most frequently in MITF, DICER1, and BRCA2, while 43 (7.9%) harbored variants in NDD-related genes, including DHCR7, POLG, and ARSA." (PMID 41844650, 2026). "However, there is still a lack of knowledge about mitochondria-related nuclear SNPs such as TFAM and POLG in cancers." (PMID 36833361, 2023). "The link between POLG rs2072267 and disease outcomes from this and our previous study suggests that POLG rs2072267 might have a role in cancer progression." (PMID 33922707, 2021). "Moreover, POLG’s role in tumor cell growth was further supported by the finding that POLG knockdown dramatically delayed cancer cell growth and cellular bioenergetics." (PMID 28359291, 2017). "For the cancer phenotypes, the reverse genetics models were enriched in DNA repair functions (p = 2×10−5, FDR p = 0.03) (POLG/FANCI, SLX4/FANCP, XRCC1, BRCA1, FANCA, CHD1L) while the additive model showed enrichment related to chromatid segregation (p = 4×10−6, FDR p = 0.005) (KIF25, PINX1)." (PMID 24349080, 2013).
myopathy (18 papers, 2013 to 2026). A disease of the muscle in which the muscle fibers do not function properly. "P3 and 4, the two affected siblings carrying the POLG variant (c.911T>G), initially presented with progressive myopathy that started with the involvement of ophthalmic muscles at 6 years of age in both average growth and neuromotor development." (PMID 37377599, 2023). "The sample included 16 participants with PEO (8 associated with single mtDNA deletion, including 3 KSS; 8 with mutations in POLG), nine with OPMD with mutations in PABPN1, and nine controls without histological or clinical evidence of myopathy." (PMID 33352713, 2020). "NGS was performed according to standard protocols and showed no pathological mutations in 251 myopathy-related genes including RYR1, POLG and other nuclear encoded mitochondrial genes." (PMID 31991853, 2020). "That myopathy was not a major feature was supported by our FGF-21 results: FGF-21 levels were also lower in the group of patients with nuclear gene mutations than it could be expected, but similar to those reported earlier in ataxic POLG patients." (PMID 33501425, 2021).
tumor (16 papers, 2015 to 2025). "This study aimed to analyze single-nucleotide variants in the POLG gene and assess the associations with tumor phenotype and patient outcome." (PMID 33922707, 2021). "We analyzed possible associations between POLG polymorphisms in genotype and allele models and available clinical and tumor data with Pearson’s Chi-square test." (PMID 33922707, 2021). "Additionally, rs11006129 was associated with the tumor differentiation grade (p = 0.036), and rs3087374 in the POLG gene was associated with tumor size (p = 0.017)." (PMID 36833361, 2023). "A second hit in a GIST is intriguing, and further studies are needed to determine the functional role of biallelic POLG inactivation in tumor development." (PMID 39594770, 2024). "Global demethylation of the HSR-GBM1 nuclear genome modified tumor-specific genes and critical mtDNA transcription and replication factors beyond POLG and TOP1MT." (PMID 37332990, 2023). "After logistic regression analysis, it was found that patients with the POLG rs3087374 CA genotype had a 4.5 times higher probability for adenocarcinoma histological tumor type than patients with CC genotype (p = 0.034; 95% CI 1.120–18.012)." (PMID 33922707, 2021). "Results indicated that POLG protein and mRNA were dramatically upregulated in tumor tissues compared to normal tissues." (PMID 28359291, 2017). "We next isolated tumor cells from the xenograft nude mice and knocked down POLG with siRNA in these tumor cells." (PMID 28359291, 2017). "The PolG gene mutations have been found in human malignancies, suggesting that PolG may have a role in decreasing OXPHOS and boosting tumorigenicity in tumor cells." (PMID 35326612, 2022). "Among these DEGs, CDKN2A, GNG7, GSDMD, and POLG are known tumor suppressors in GC." (PMID 36230863, 2022). "However, in our study, the POLG rs3087374 CA genotype was associated with an increased risk of adenocarcinoma histological tumor type, IIIA stage, and T3 tumor size compared to the CC genotype." (PMID 33922707, 2021). "As such, the curcumin-induced downregulation of POLG may also inhibited tumor cell growth through in part by decreasing mtDNA and the consequent cellular bioenergetics." (PMID 28359291, 2017). "Results indicated that EIF2AK3 and POLG expression levels correlated with the TCR CDR3-DDX53 Combo CSs, consistent with a higher proliferation rate for the tumor cells representing the higher CSs and worse DFS probabilities." (PMID 37953875, 2023). "Treatments demethylating the POLG, TOP1MT, and TFAM genes attempt to increase tumor cell mtDNA copy number, differentiation, and apoptosis." (PMID 37332990, 2023). "ESRRA, NRF1, POLG, PPARGCA1 and SIRT1 were identified to be significantly down-regulated in all of the mtDNA-depleted tumours." (PMID 30208958, 2018). "Additionally, we found 50% of the tumour-matched SAPCS POLE, POLQ, and POLG carriers to present with an above median TMB." (PMID 41038821, 2025).
peripheral neuropathy (14 papers, 2009 to 2026). A disorder affecting the peripheral nervous system. "Recently, a diagnostic flow-chart has been suggested for POLG-related diseases in pauci-symptomatic patients affected by peripheral neuropathy and suspected mitochondrial impairment." (PMID 26251896, 2015). "In the present study, 69% of patients with PEO due to POLG mutations had peripheral neuropathy, a higher figure than previously reported, and POLG mutations were the commonest cause of peripheral neuropathy." (PMID 25281868, 2014). "The results indicate that peripheral neuropathy is a rare finding in patients with single mitochondrial DNA deletions and that the presence of peripheral neuropathy is highly predictive of an underlying nuclear DNA defect, particularly POLG mutations." (PMID 25281868, 2014). "Peripheral neuropathy, even if not exclusive, is often associated with POLG mutations; however, it also occurs in PEO1 cases." (PMID 26251896, 2015). "This is an important finding because until now peripheral neuropathy has not been described in patients with RRM2B mutation, but only in patients with POLG mutation." (PMID 24382854, 2013).
infection (9 papers, 2017 to 2025). The state of being infected such as from the introduction of a foreign agent such as serum, vaccine, antigenic substance or organism. "Recognizing the interactions between genotype and environmental factors, such as infections, is essential for understanding the mechanisms underlying POLG-related diseases and improving therapeutic strategies." (PMID 39958089, 2025). "Notably, a series of cases indicated that 12 out of 15 children with confirmed POLG mutations presented their initial symptoms within 3-10 days following an intercurrent infection." (PMID 39958089, 2025). "The results revealed that 48 h after infection with B. abortus A19, the mRNA expression of mtDNA2-6, POLG, SSBP1, and TOP1 in the BTC group was significantly greater than that in the control group." (PMID 40317067, 2025). "Infection with E. coli increased expression of polymerase gamma (POLG), single-stranded DNA-binding protein (SSBP1), TWINKLE (TWNK), and DNA topoisomerase 1 (TOP1) genes." (PMID 36430657, 2022). "At the early stage of infection, H. pylori induce VacA dependent dysregulation of mitochondria hemostasis, which promotes transient increase in mitochondrial translocases, mitochondrial DNA replication maintenance factors such as POLG and TFAM." (PMID 39906209, 2024). "Later upon infection, POLG signal progressively decreased to control levels, as confirmed by WB." (PMID 29162845, 2017). "First, early upon infection VacA induces transient increase of mitochondrial translocases and a dramatic accumulation of the mitochondrial DNA replication and maintenance factors POLG and TFAM." (PMID 29162845, 2017). "Thus, increase of POLG also occurred independently of VacA but to a lower extent and delayed compared to the wild-type infection, suggesting that H. pylori activities other than VacA can modulate POLG levels." (PMID 29162845, 2017). "Importantly, mutations in the mitochondrial replisome’s proteins POLG, TFAM, and MGME1 genes are associated with the accumulation of mtDNA deletions that may also increase susceptibility for infection-induced chronic-inflammation-associated disease." (PMID 39906209, 2024). "While infections do not directly cause AHS, they can reveal or trigger the disease in previously asymptomatic children or young adults with POLG mutations, thereby accelerating the stepwise progression of the disorder." (PMID 39958089, 2025). "Treatment of HeLa cells with 50 μM H2O2 did not enhance POLG/PARP1 interaction to the same extent as was noted with Tc infection." (PMID 29851986, 2018). "A further novel finding concerns VacA-independent mitochondrial deregulation, observed in H. pylori 26695∆vacA-infected cells, where TOM22, TIM23, POLG and TFAM were induced shortly upon infection, although at a lower extent and delayed compared to 26695 infection." (PMID 29162845, 2017). "Conversely, in the absence of VacA, POLG was initially concentrated in a few mitochondria (6.42 ± 0.9% of the signal at 2 h) but later upon infection the situation becomes similar as for the wild-type strain." (PMID 29162845, 2017). "Therefore, the late POLG and TFAM up-regulation in vivo could likely be VacA-independent, as observed at late infection time-points in vitro." (PMID 29162845, 2017). "Thus, early upon infection and in the absence of VacA, only a small fraction of mitochondria was enriched in POLG and TFAM, despite extramitochondrial POLG and to a minor extent TFAM were observed with either H. pylori strains." (PMID 29162845, 2017).
movement disorder (7 papers, 2013 to 2025). Neurological conditions resulting in abnormal voluntary or involuntary movement, which may impact the speed, fluency, quality and ease of movement. "We report the movement disorder semiology and neurotransmitter profiles in children with biallelic POLG mutations." (PMID 30167885, 2018). "In this study, we aimed to describe the clinical spectrum of movement disorders and cerebrospinal fluid (CSF) neurotransmitter profiles in children with POLG mutations." (PMID 30167885, 2018). "POLG disease has previously been associated with a wide range of movement disorders." (PMID 30167885, 2018). "All 20 patients with a movement disorder had biallelic POLG mutations." (PMID 30167885, 2018). "The pathogenic m.8344A > G and POLG variants were always associated with a movement disorder, while LHON variants and mtDNA single deletions were more commonly found in the subjects who did not present a movement disorder." (PMID 34259909, 2022).
neurodegenerative disease (5 papers, 2022 to 2024). A disorder of the central nervous system characterized by gradual and progressive loss of neural tissue and neurologic function. "POLG mutations also drive changes in mtDNA and respiratory chain complex I that mimic what is seen in neurodegenerative disease such as PD and AD making POLG disease an excellent model for studying the mitochondrial component of neurodegeneration." (PMID 38904024, 2024).
neurological disease (4 papers, 2014 to 2025). "Pathogenic POLG variants cause inherited mitochondrial depletion syndromes, resulting in a range of neurological disorders with differing symptoms and severity." (PMID 41292636, 2025). "As proof of concept, we apply this method on brain tissue from patients with neurological disease caused by mutations in the mitochondrial DNA polymerase gamma (POLG)." (PMID 40114250, 2025). "POLG mutations are linked to a wide range of systemic or neurological diseases." (PMID 30941926, 2019).
genetic disorder (3 papers, 2012 to 2024). "Its pathogenesis is associated with mutations in the DNA Polymerase Gamma, Catalytic Subunit (POLG) gene, which can manifest as either an autosomal dominant or recessive genetic disorder." (PMID 39095891, 2024).
kidney disease (2 papers, 2021 to 2025). "In addition, while some identified variants (e.g., P779; POLG, P577; PHEX) are not classified as primary kidney disease genes, their detection had significant clinical implications, including avoiding nephrotoxic medications, guiding peri-transplant care, and informing family genetic counseling." (PMID 40282368, 2025).
cardiovascular disease (1 paper, 2024). "Mitochondrial dysfunction (acquired and inherited) is known to promote cardiovascular disease, but the extent to which genetic variants in the POLG gene might contribute to vascular dysfunction is not well understood." (PMID 40034369, 2024).